BMP6 (bone morphogenetic protein 6)
Diseases named in the same sentence as BMP6 in open-access papers (continued):
Sharing a sentence is not in itself a finding about the gene and the disease.
sickle cell disease (3 papers, 2014 to 2024). Sickle cell anemias are chronic hemolytic diseases that may induce three types of acute accidents: severe anemia, severe bacterial infections, and ischemic vasoocclusive accidents (VOA) caused by sickle-shaped red blood cells obstructing small blood vessels and capillaries. "Furthermore, the Cooperative Study of Sickle Cell Disease (CSSCD) DNA samples have identified certain candidate gene SNPs (e.g., BMP6, annexin A2, and klotho) as risk factors for the development of avascular necrosis of the hip and/or shoulder." (PMID 39113817, 2024). "The results indicate that the polymorphisms in BMP6, Klotho and ANXA2 genes may be associated with avascular necrosis in patients with sickle cell disease." (PMID 35584416, 2022). "The results indicate that polymorphisms in the genes of the bone morphogenetic protein 6 (BMP6), Klotho (KL) and Annexin A2 (ANXA2) may be associated with osteonecrosis in the context of sickle cell disease." (PMID 35584416, 2022).
asthma (2 papers, 2014 to 2021). "Of these genes, CFB was induced in all patients, whereas BMP6 solely in allergic rhinitis patients and MYLK in allergic rhinitis patients with asthma." (PMID 24475887, 2014).
atherosclerosis (2 papers, 2024 to 2026). A disease characterized by the build-up of fatty material and calcium deposition in the arterial wall resulting in partial or complete occlusion of the arterial lumen. "Several investigations have highlighted the ability of BMP-2, BMP-4, and BMP-6 to stimulate the development of vascular calcification in association with atherosclerosis." (PMID 38540696, 2024). "Kyoto Encyclopedia of Genes and Genomes (KEGG) functional enrichment analysis revealed that EC3 was associated with the TGF‐β signaling pathway and fluid shear stress and atherosclerosis, suggesting a potential link between BMP6 and atherosclerosis." (PMID 41082328, 2026). "BMP-6 and ox-LDL synergistically induce osteogenic differentiation and mineralization, highlighting an important connection between BMP signaling, oxidative stress, and inflammation in vascular calcification associated with atherosclerosis." (PMID 38540696, 2024).
Autoimmunity (2 papers, 2022). The occurrence of an immune reaction against the organism's own cells or tissues. "The newly identified LAMP3/HSP70/BMP6 axis provided an etiological model for SS gland dysfunction and autoimmunity." (PMID 35113815, 2022). "Both NK activation and autoimmunity are linked to BMP signaling, e.g., via an autocrine activation pathway via BMP receptors and BMP ligands in NK cells, which fits our identified target genes BMP1, BMP2, BMP3, BMP7, BMP6, BMPER, BMPR1B, and, most importantly, BMPR2." (PMID 35455956, 2022).
B-cell lymphoma (2 papers, 2012 to 2024). "Second, PRC2 represses the expression of BMP6, BMP7, and ACVR1 by H3K27me3 in B cell lymphoma in vitro and in vivo." (PMID 38229201, 2024). "Together, this study identifies and demonstrates that BMP6/7‐ACVR1 signaling is a downstream pathway of PRC2 and plays an essential role in the efficacy of PRC2 inhibitors in B‐cell lymphoma treatment." (PMID 38229201, 2024). "As malignant B cells expressed BMP6 and BMP7, we next studied the effects of exogenously added BMPs in different B-cell lymphoma cell lines." (PMID 23049692, 2012). "Finally, the high levels of BMP6, BMP7, and ACVR1 correlate with a favorable survival outcome in B‐cell lymphoma patients." (PMID 38229201, 2024).
benign prostate hyperplasia (2 papers, 2023 to 2025). "In comparison with benign prostate hyperplasia, the expression of BMP-6 is upregulated in PCa, especially in metastatic PCa." (PMID 37664042, 2023).
bladder cancer (2 papers, 2022 to 2024). "The expression of BMP6, a key endogenous regulator of iron metabolism, was affected by Med19, which could promote bone metastasis and invasiveness of bladder cancer." (PMID 35265613, 2022). "Public clinical data also confirm that BMP6 is a prognostic marker for bladder cancer." (PMID 35265613, 2022). "FASN, MAP2 and BMP6 were highly expressed in bladder cancer, while GPC2, CNOT6L, GALNT12 and CARD10 were expressed at low levels in bladder cancer." (PMID 38218866, 2024).
bone cancer (2 papers, 2009 to 2020). A primary or metastatic malignant neoplasm affecting the bone or articular cartilage. "Interestingly, the CMT-U309 clones, 4 and C6, that formed bone tumors in the mice expressed BMP-6." (PMID 19771160, 2009).
cavernomas (2 papers, 2016 to 2019). "Overall, these data are suggestive of a role of BMP6, possibly in combination with other inflammatory cytokines, in the attraction of wild-type endothelial cells in the cavernomas by Ccm3−/− cells." (PMID 31235698, 2019). "Immunohistochemical analysis of brain tissues confirmed BMP6 reduction in ECs lining the cavernomas of iCCM1/KLF4 mice compared to iCCM1 animals." (PMID 26612856, 2016).
chondrosarcoma (2 papers, 2012 to 2017). A malignant cartilaginous matrix-producing mesenchymal neoplasm arising from the bone and soft tissue. "Second, PEG10 expression was suppressed by TGF-β1 stimulation in chondrosarcoma cells, while activation of the R-SMAD pathway by TGF-β1 or BMP-6 stimulation was mildly inhibited by PEG10." (PMID 29044189, 2017). "As positive controls, SB431542 and LDN193189 inhibitors completely abolished TGF-β1-induced SMAD3 phosphorylation and BMP-6-mediated activation of SMAD1/5/9, respectively, in both SW1353 and Hs 819.T chondrosarcoma cell lines (lanes 4–7 and 11–14)." (PMID 29044189, 2017).
colitis (2 papers, 2022 to 2023). Inflammation of the colon. "A prior work on zebrafish utilising TNBS-induced mice found increased expression of BMP7 in the acute phase and BMP6 in the chronic phase of colitis." (PMID 36500396, 2022). "In this review, we concluded that anti-BMP6 reagents, exogenous BMP7 and FST all have impacts on decreasing IBD-associated pro-inflammatory cytokines, especially IL-6 which attenuates DSS-induced mice colitis." (PMID 37391444, 2023).
injury (2 papers, 2024 to 2025). Damage inflicted on the body as the direct or indirect result of an external force, with or without disruption of structural continuity. "Bmp6 has been implicated as a mediator of angiogenesis and lung vascular permeability associated with acute lung injury." (PMID 39513364, 2024). "In conclusion, we provide evidence that BMP6 might be a new biomarker and a potential pharmacological target for APAP-induced acute liver injury." (PMID 39827450, 2025).
kidney cancer (2 papers, 2020 to 2024). Primary or metastatic malignant neoplasm involving the kidney. "Several genes showed a low gDS in most kidney cancer cell lines, such as CD82, CD7, MEST, SELP, BMP6, CA2, DNAJC6, and VEPH1." (PMID 38728235, 2024).
myocardial infarction (2 papers, 2022 to 2023). Gross necrosis of the myocardium, as a result of interruption of the blood supply to the area, as in coronary thrombosis. "In this paper, we demonstrated that BMP6 expression was upregulated after myocardial infarction in wild‐type (WT) mice." (PMID 37313693, 2023). "The HE staining results also revealed more severe inflammatory infiltration in BMP6 knockout mice after myocardial infarction." (PMID 37313693, 2023). "Based on our findings, we observed a more significant degree of myocardial fibrosis in the BMP6 knockout mice following myocardial infarction compared to the WT mice, which is consistent with previous results." (PMID 37313693, 2023). "After knocking down BMP6 expression, hypoxia‐stimulated fibroblasts were used to simulate a myocardial infarction model in vitro." (PMID 37313693, 2023). "The serum BMP6 was upregulated, indicating BMP6 function as a marker for predicting myocardial infarction." (PMID 37313693, 2023). "Additionally, BMP6 expression was found to be decreased in myocardial infarction and considered as a marker of recurrence." (PMID 35625854, 2022). "Therefore, BMP6 may be a novel molecular target for improving myocardial fibrosis and cardiac function after myocardial infarction." (PMID 37313693, 2023). "This study aimed to investigate how BMP6 functioned in cardiac fibrosis following myocardial infarction (MI)." (PMID 37313693, 2023).
pneumonia (2 papers, 2024). An acute, acute and chronic, or chronic inflammation focally or diffusely affecting the lung parenchyma, caused by an infection in one or both of the lungs (by bacteria, viruses, fungi, or mycoplasma.). "Furthermore, underlying conditions that lead to SIRS or sepsis, such as cholangitis, pneumonia, or urinary tract infections, did not affect plasma BMP6 levels." (PMID 39200147, 2024).
polycystic ovary syndrome (2 papers, 2022 to 2024). A disorder that manifests as multiple cysts on the ovaries. "Previous studies have shown that several BMPs, including BMP2, BMP4, BMP5, BMP6, BMP7 and BMP8A are expressed in the granulosa cells from normally cycling and polycystic ovary syndrome women." (PMID 35395768, 2022).
pulmonary hypertension (2 papers, 2014 to 2024). Increased pressure within the pulmonary circulation due to lung or heart disorder. "A previous study by Nick Morrell’s laboratory revealed that TNFα promotes pulmonary hypertension by repressing BMPR-II signaling and enhancing BMP6, which, in turn, stimulates SMC proliferation via ALK2 and ACTR-IIA." (PMID 39273443, 2024).
renal carcinoma (2 papers, 2010 to 2015). A carcinoma arising from the epithelium of the renal parenchyma or the renal pelvis. "It has been reported that BMP6 promotes tumor proliferation through IL-10-dependent M2 polarization of tumor-associated macrophages in renal carcinoma." (PMID 26029998, 2015). "The same report further demonstrated that BMP-6, a close family member of BMP-7 inhibited human renal carcinoma cell line 112 in a dose dependent manner." (PMID 23675191, 2010). "BMP-6 did not appear to have any effect on three human renal carcinoma cell lines 112, 117, and 181, seemingly due to a decreased BMPR-II expression." (PMID 23675191, 2010).
Sepsis (2 papers, 2024 to 2025). Sepsis is defined as life-threatening organ dysfunction caused by a dysregulated host response to infection. "Furthermore, the associations between plasma BMP6 levels and the need for dialysis, ventilation, or vasopressor treatment in patients with sepsis/septic shock were examined." (PMID 39200147, 2024). "The current study shows that sepsis and septic shock patients have reduced plasma BMP6 levels, while levels are normal in SIRS patients." (PMID 39200147, 2024). "Both men and women in the SIRS (26 males and 12 females) and the sepsis/septic shock group (84 males and 33 females) had comparable BMP6 levels (p = 0.593 and p = 0.138, respectively)." (PMID 39200147, 2024). "BMP6 was still lower in SIRS (p = 0.006) compared to sepsis/septic shock when patients with liver cirrhosis were excluded." (PMID 39200147, 2024). "An analysis of 38 SIRS, 39 sepsis, and 78 septic shock patients revealed similar levels of BMP6 in sepsis and septic shock, which were lower compared to patients with SIRS and healthy controls." (PMID 39200147, 2024). "Because of this difference between SIRS and sepsis/septic shock, further calculations of BMP6 levels were performed separately in these cohorts." (PMID 39200147, 2024). "Plasma BMP6 levels were similar between these groups (p = 0.665 for sepsis/septic shock and p = 0.935 for SIRS)." (PMID 39200147, 2024). "Our study aimed to evaluate the associations between plasma BMP6 levels and disease severity and outcomes in patients with systemic inflammatory response syndrome (SIRS), sepsis, or septic shock." (PMID 39200147, 2024). "BMP6 in the plasma of sepsis and septic shock patients was decreased compared to SIRS patients and healthy controls." (PMID 39200147, 2024). "Panel three adds PLEKHO1 and BMP6, showing perfect classification in two sepsis plasma datasets." (PMID 40665987, 2025). "This suggests that lower plasma BMP6 levels are associated with sepsis itself rather than the triggering condition." (PMID 39200147, 2024). "Our data show that plasma BMP6 levels in sepsis and septic shock patients are reduced." (PMID 39200147, 2024). "Critically ill patients often have hyperglycemia because of impaired insulin activity; however, whether low BMP6 levels of patients with sepsis/septic shock contribute to metabolic pathophysiology in these patients requires further study." (PMID 39200147, 2024). "ELISA was used to measure plasma BMP6 levels in 38 patients with SIRS and 117 patients with sepsis or septic shock." (PMID 39200147, 2024). "Plasma BMP6 concentrations were 145 (0–6746) pg/mL in the 38 patients with SIRS, 0 (0–1728) pg/mL in the 39 sepsis patients, and 6 (0–4600) pg/mL in the 78 patients with septic shock." (PMID 39200147, 2024). "In conclusion, this study showed normal BMP6 plasma levels in SIRS, which are reduced in patients with sepsis and septic shock." (PMID 39200147, 2024). "The current analysis showed that plasma BMP6 levels are normal in SIRS patients and are reduced in patients with sepsis and septic shock." (PMID 39200147, 2024). "Specifically, increased expression of NONO and BMP6 correlates with a greater likelihood of severe sepsis." (PMID 40665987, 2025). "This suggests that the commonly observed increase in hepcidin levels and the decline in iron levels in SIRS, sepsis, and septic shock are not due to higher BMP6." (PMID 39200147, 2024). "Plasma BMP6 levels in sepsis/septic shock patients with positive blood cultures were not altered, and this excludes BMP6 as a marker of bacterial infection." (PMID 39200147, 2024). "There was a modest negative correlation of plasma BMP6 with age in the sepsis/septic shock cohort, which was not seen in SIRS and controls." (PMID 39200147, 2024). "BMP6 is abundant in circulation but has, to the best of our knowledge, not been measured in patients with sepsis or septic shock." (PMID 39200147, 2024).
Sepsis (continued). "Given that BMP6 is not related to hepcidin and iron metabolism in severe illness, it is not unexpected that BMP6 plasma levels of patients with sepsis/septic shock were not correlated with CRP, procalcitonin, or white blood cell counts." (PMID 39200147, 2024). "Plasma BMP6 levels in sepsis/septic shock patients without bacterial infection were comparable to those with Gram-negative (twelve patients), Gram-positive (nineteen patients), or mixed bacterial infections (four patients) (p = 0.250)." (PMID 39200147, 2024). "While literature links NONO, FCAR, BMP6, RNF4, and RNASE2 to sepsis or Systemic Inflammatory Response Syndrome (SIRS), their interactions and the roles of PLEKHO1, OGFOD3, and CKAP4 in sepsis are less documented." (PMID 40665987, 2025). "Using our new plasma data (11 septic shock samples and 21 sepsis samples), the combinations of five genes (NONO, CKAP4, FCAR, PLEKHO1, BMP6) reached an overall accuracy of 93.75%, with a sensitivity of 81.82% and a specificity of 100.00%." (PMID 40665987, 2025). "We observe a clear relationship between gene expression and sepsis severity based on the plasma analysis from GSE49757 and the coefficient signs for the genes NONO, CKAP4, PLEKHO1, and BMP6." (PMID 40665987, 2025). "BMP6 did not correlate with ferritin (r = −0.024, p = 0.823), iron (r =−0.084, p = 0.467), or transferrin (r = −0.006, p = 0.958) in SIRS/sepsis/septic shock patients when patients with liver cirrhosis were excluded." (PMID 39200147, 2024). "BMP6 levels of the patients were not related to the BMI (r = 0.104, p = 0.541 for SIRS and r = −0.152, p = 0.101 for sepsis/septic shock)." (PMID 39200147, 2024). "BMP6 did not correlate with leukocyte numbers, procalcitonin, CRP, or IL-6 in the sepsis/septic shock group (p > 0.05 for all) or in the SIRS/sepsis/septic shock cohort when patients with liver cirrhosis were excluded." (PMID 39200147, 2024). "Although BMP6 was lower in sepsis and septic shock compared to SIRS, it is not a suitable biomarker for the diagnosis of sepsis due to the high variability of plasma BMP6 levels." (PMID 39200147, 2024). "Plasma BMP6 levels did not correlate with procalcitonin and C-reactive protein levels in patients with SIRS or sepsis/septic shock." (PMID 39200147, 2024). "Bone morphogenetic protein 6 (BMP6), a key regulator of hepcidin expression, has not yet been analyzed in the plasma of patients with systemic inflammatory response syndrome (SIRS) or sepsis." (PMID 39200147, 2024).
Stroke (2 papers, 2009 to 2026). Sudden impairment of blood flow to a part of the brain due to occlusion or rupture of an artery to the brain. "The preliminary data suggested that BMP6 mutations could significantly increase the 3‐month and 1‐year risks of stroke recurrence in patients with large artery atherosclerosis." (PMID 41082328, 2026). "Both EDN1 and BMP6 are on chromosome 6 (at 6p24.1 and 6p24.3, respectively), and their association suggests that this chromosomal region may be associated with an increased risk of stroke." (PMID 20401335, 2009). "This network of interactions included three genes, BMP6, TGFBR2, TGFBR3 with a functional role in the TGF-beta pathway and one gene (SELP) associated with stroke in the general population." (PMID 20401335, 2009). "They suggest that these model variants in BMP6 are the strongest risk factors, whereas variants in EDN1 are associated with stroke through BMP6 and ANXA2 but are not as relevant for the risk prediction." (PMID 20401335, 2009). "BMP6 is part of the TGF-beta super-family, and the simultaneous association of three genes with functional roles in TGF-betạ signaling suggests that this pathway might be involved with increased risk of stroke." (PMID 20401335, 2009).
Zika virus infection (2 papers, 2022 to 2024). "To further validate the association between the antiviral response against ZIKV infection and BMP6 signaling, we first tested if BMP6 expression is under the control of IFN-β in SC and two other cell types (A549 and BMVEC)." (PMID 36713156, 2022). "A recent study on human Sertoli cells showed that Zika virus infection can counteract BMP6 signaling, and that BMP6 induces phosphorylation of IRF3 and STAT1, and increases expression of IFNβ and some ISGs." (PMID 38308064, 2024). "Together, these data suggest that BMP6 signaling is suppressed in SC at later stages of ZIKV infection and is one of the modulators of anti-ZIKV response in this cell type." (PMID 36713156, 2022).
adenoma (1 paper, 2007). A neoplasm arising from the epithelium. "Importantly, BMP-6 expression was significantly increased and was most intense in the vicinity of chondroid matrix of complex adenomas and mixed benign tumors of canine mammary glands." (PMID 17997862, 2007).
advanced heart failure (1 paper, 2023). Patients with advanced heart failure have severe limitations, experiences symptoms even while at rest and are mostly bedbound patients. "Our results showed that BMP6 protein expression was upregulated after MI, which was consistent with a clinical study that found elevated BMP6 expression among the sera of patients with advanced heart failure." (PMID 37313693, 2023).
ankylosis (1 paper, 2014). Fixation and immobility of a joint. "In summary, we show that certain BMP6 polymorphisms, especially rs270378 and rs1235192, are possible risk factors for the development of syndesmophyte and ankylosis in AS." (PMID 25121767, 2014). "We demonstrated for the first time that SNPs in BMP6 likely play a contributory role in syndesmophyte formation or ankylosis in AS." (PMID 25121767, 2014). "However, further study investigating human histologic finding is needed to demonstrate the biologic role of BMP6 in syndesmophyte or ankylosis formation in human AS." (PMID 25121767, 2014).